INS (insulin)
Diseases named in the same sentence as INS in open-access papers (continued):
Sharing a sentence is not in itself a finding about the gene and the disease.
Insulin resistance (continued). "On one hand, the reduction in the density of IRs in the plasma membrane of target tissues may affect glucose handling, indicating that insulin resistance is a byproduct of an impaired insulin signaling." (PMID 24995000, 2014). "This tissue‐specific insulin resistance may contribute to the overall disease state in type 2 diabetes and can be accompanied by a doubling of fasting insulin concentrations." (PMID 25347855, 2014). "Insulin resistance refers to a decrease in the biological and physiological response to insulin, resulting in over secretion of insulin to compensate for the impairment of glucose transport into skeletal muscle and fat cells and inhibition of liver glycogen production." (PMID 25674108, 2014). "We ascertained that the pre-treatment with 10 ng/mL TNF-α for 2 hours induced insulin resistance in both vascular cells as shown by the significant decreases in the phosphorylation of Akt, p70S6K and p44/42 in cells stimulated with 10 nmol/L insulin for 10 minutes." (PMID 25077985, 2014). "In patients with metabolic syndrome, insulin resistance results in the impaired insulin activities in tissues like muscle, liver, kidney and fat leading to increase oxidative stress, pro-coagulant/anti-fibrinolytic and chronic pro-inflammatory state coupled with platelet hyper-aggregality." (PMID 24919841, 2014). "Thiazolidinedione (TZD) insulin sensitizing agents may reverse the abnormalities by ameliorating insulin resistance, which have been used to prevent the progression of NAFLD in clinical studies." (PMID 24799887, 2014). "Similarly, recent research on experimental models has underlined how some bioproducts of lipid peroxidation, such as HNE and ONE, are able to induce structural and functional changes in human insulin and how HNE causes insulin resistance." (PMID 24987495, 2014). "Likewise, a recent report observed decreased myogenic activity, but preserved endothelial activity, during transdermal insulin administration in severely obese adolescents showing moderate hyperinsulinemia and insulin resistance." (PMID 24399971, 2013). "It has been observed that high insulin concentrations often relate to insulin resistance." (PMID 23398686, 2013). "Third, increased, rather than decreased, insulin signaling in the endothelium predisposes to systemic insulin resistance." (PMID 24399971, 2013). "However, 10% fructose administration in drinking water resulted in significant hyperinsulinemia, and insulin resistance in 6 weeks in the insulin resistant model." (PMID 23717483, 2013). "Insulin resistance is defined as a reduced ability of insulin to stimulate glucose utilization." (PMID 23899788, 2013). "This insulin resistance may partly antagonise the insulin hypersecretion derived from the sulfamethoxazole component of cotrimoxazole." (PMID 24083038, 2013). "Because exercise improves muscular insulin sensitivity through a variety of mechanisms, high levels of CRF with regular exercise may have a protective effect against insulin resistance associated with low birth weight." (PMID 24069257, 2013). "Hepatic insulin resistance, characterized by a defect in insulin-induced PI3K-Akt signal transduction, rapidly develops within 90 minutes following T-HS, but may have been alleviated within 48 hours post-T-HS in the present study." (PMID 24204984, 2013). "As TNF-α induced insulin resistance and miR-494 expression, we tested whether miR-494 can modulate insulin action." (PMID 24349514, 2013). "This acts as a stimulus for pancreatic beta cells to augment insulin secretion to maintain normal glucose homeostasis; however, long-term hyperglycemia impairs the insulin signaling pathway and depresses the sensitivity to insulin, leading to glucose intolerance and insulin resistance." (PMID 23573121, 2013).
Insulin resistance (continued). "We have previously shown that troglitazone, a clinically validated insulin sensitizer reversed dexamethasone-induced insulin resistance in 3T3 adipocytes and the role of insulin signaling molecules in the development of insulin resistance has also been demonstrated." (PMID 24194903, 2013). "No significant changes in lipids (total cholesterol, HDL cholesterol, LDL cholesterol, or triglycerides), glucose, insulin, or the homeostasis model assessment of insulin resistance (HOMA-IR) were observed overall or in any sub-group 24 weeks after initiating telmisartan therapy." (PMID 23516440, 2013). "To examine whether Pdk2 or Pdk4 knockout might affect insulin resistance in IrsLDKO mice, we performed insulin tolerance tests." (PMID 23940800, 2013). "This increased intracellular calcium may compromise the insulin responsiveness of adipocytes and skeletal muscles leading to the development of insulin resistance." (PMID 24065990, 2013). "Because the IRS1 serine 307-kinase catalyzes a critical step in the control of insulin signaling and constitutes a potential target for treatment of insulin resistance, it is important to know whether S6K1 is the physiological serine 307-kinase or not." (PMID 23565163, 2013). "Second, it is possible that prolonged treatment of L6 muscle cells in the presence of insulin may have induced insulin resistance." (PMID 24260440, 2013). "In addition, the offspring of diabetic mothers revealed a state of tissue insulin resistance and decreased insulin sensitivity." (PMID 23998129, 2013). "Biochemical analysis was done for serum glucose, serum insulin and insulin resistance." (PMID 24555069, 2013). "Homeostasis model assessment (HOMA) was used to assess pancreatic cell function (HOMA B) and insulin resistance (HOMA IR) using fasting insulin and glucose concentrations by the formula: HOMA-B (%) =20 X [insulin]/(glucose.3,5) and HOMA-IR = insulin/(22,5e.ln[glucose])." (PMID 23497407, 2013). "This aspect raises the possibility that insulin glycation might contribute to insulin resistance and glucose intolerance in type 2 diabetes." (PMID 23365488, 2013). "In addition, iron excess probably contributes initially to insulin resistance and subsequently to decreased insulin secretion." (PMID 24098686, 2013). "Different severity or condition of type 2 diabetes might result in different insulin resistance, and taking different oral hypoglycemia agents might also influence insulin sensitivity." (PMID 23431295, 2013). "So we hypothesized that, under diabetic conditions, ERS is reduced, the insulin signaling pathway is inhibited, and insulin resistance is worsened by activation of JNK in the CNS." (PMID 23829668, 2013). "In addition, PTEN has been shown to be upregulated in insulin resistance model of insulin/insulin-like growth factor-1 signaling ablation in β-cells." (PMID 23431468, 2013). "Ang II may be responsible for triggering inflammation by inducing oxidative stress, abnormalities of islet blood flow regulation, lipotoxicity and by negatively modulating insulin signaling, resulting in insulin resistance and endocrine pancreas dysfunction." (PMID 23894285, 2013). "Moreover, glucose- and insulin tolerance test demonstrated the amelioration of insulin resistance by LNA-miR-146b antagomir." (PMID 24009212, 2013). "However, MCD mice have a decreased intrahepatic insulin resistance with reduced phosphorylation of Akt in response to an insulin stimulus." (PMID 24204981, 2013). "As TNF-α is a major mediator in the inflammatory process that is considered an inducer of insulin resistance (reviewed in 51,52), we investigated whether insulin signaling may be affected by TNF-α in C2C12 myotubes." (PMID 24349514, 2013). "Thus, the activity of InsR, IRS, PI3K, and PPARγ is important in mediating the metabolic effects of insulin and closely correlative with insulin resistance." (PMID 23762123, 2013).
Insulin resistance (continued). "Inhibition of muscle insulin signaling and insulin resistance inhibits insulin action on adipose glucose uptake and lipid synthesis, further increasing the rate of FFA release into the circulation, and contributes to the development of insulin resistance and type 2 diabetes." (PMID 23653642, 2013). "In addition, soy protein and isoflavonoids in soybeans improve insulin resistance and enhancement of insulin release." (PMID 23662132, 2013). "Effect of fructose- induced insulin resistance (IR, 10% in drinking water, for 12 weeks) and daily oral administration of quercetin (50 mg.kg−1) on body weight, blood glucose, serum insulin, insulin resistance (IR) index, TNF-α, C-reactive protein (CRP), systolic BP." (PMID 23717483, 2013). "However, despite those numerous studies on insulin resistance in AI, less attention has been paid to insulin secretion, another important predictor of T2DM development, as observed in T2DM–prone offspring of T2DM patients." (PMID 24146977, 2013). "Obesity is of particular importance and a prolonged positive energy balance with subsequent lipid deposition and expansion of adipose depots, particularly visceral depots which secrete inflammatory cytokines, play a role in insulin resistance and decreased insulin-mediated glucose uptake." (PMID 23822206, 2013). "Increased GLP-1 concentrations in states of metabolic risk like hypertriglyceridemia could represent a counter regulation to increase insulin secretion in states of insulin resistance." (PMID 23953602, 2013). "ITT may be a useful method for assessing insulin resistance (IR) and predicting the effectiveness of insulin sensitizers." (PMID 24131482, 2013). "Because serum insulin levels and glucose tolerance might be altered due to peripheral insulin resistance, we then measured insulin sensitivity in S2814D mice using the insulin tolerance test (ITT)." (PMID 23516528, 2013). "Adiponectin concentrations are mostly linked to insulin sensitivity independent on BMI as a measure of adiposity and not to insulin resistance in type 2 diabetic Sudanese subjects." (PMID 23497407, 2013). "According to previous studies, lipid and fatty acids may induce insulin resistance by blunting insulin sensitivity through inhibition of glycolysis at key points." (PMID 23431295, 2013). "However, higher insulin levels and a greater degree of insulin resistance were noted among PsA patients, and these remained significant even after controlling for BMI and CRP." (PMID 23843781, 2013). "In addition, we distinguish the exercise modality for enhancing insulin sensitivity, which should be recommended for the treatment of insulin resistance in this age group." (PMID 24454364, 2013). "The limitations of our study include the fact that we did not study women or subjects of other ethnicities, and we estimated insulin resistance by Matsuda Index, widely-accepted approaches to studying insulin resistance in large numbers, where clamp methods are inapplicable." (PMID 24116041, 2013). "Therefore, HFD for 6 weeks is sufficient to induce insulin resistance leading to an increased demand for insulin from beta cells." (PMID 23441226, 2013). "Impaired Wnt/β-catenin signaling pathway in skeletal muscle has also been found, which may also participate in pathogenesis of insulin resistance in adult life, since the insulin sensitivity can be improved by activating Wnt/β-catenin." (PMID 24455747, 2013). "To test whether the association between insulin and FGF-21 mRNA in muscle reflect an association with peripheral or hepatic insulin resistance, we performed a euglycemic-hyperinsulinemic clamp with stable isotopes." (PMID 23533568, 2013). "Obesity related insulin resistance and excessive insulin synthesis in women may contribute to hyperandrogenism and anovulatory infertility through several pathways as insulin is a potent regulator of sexual steroid production in the endocrine organs." (PMID 23061769, 2013).
Insulin resistance (continued). "Therefore we focused specifically on insulin resistance to investigate clinically the potential role of insulin in breast carcinogenesis." (PMID 23497533, 2013). "The data of the present study seems to indicate that MS, particularly insulin resistance, in the postmenopausal population, may be ameliorated by insulin-sensitizing supplementation." (PMID 23981814, 2013). "Insulin resistance (IR) is a defect of insulin-mediated cellular glucose uptake, which may elicit many disorders in the gene regulation of cellular metabolism, growth, differentiation and mitotic activity." (PMID 23061769, 2013). "Replacing saturated fat with carbohydrates may increase daily blood glucose level because it requires more insulin to maintain glucose homoeostasis, which is demanding in individuals with insulin resistance." (PMID 24634801, 2013). "We suggest that these data point towards a previously uncharacterised potential role for SPARC in moderation of insulin secretion, separate from the anti-proliferative and profibrotic function of this protein in adipose tissue where it appears to be a moderator of insulin resistance." (PMID 23840838, 2013). "Insulin resistance inhibits glucose uptake creating a situation of severe detriment given both fatty acid and glucose metabolism are impaired and energy provision is compromised in the insulin resistant, infarcted heart." (PMID 24007410, 2013). "In patients with sub-optimal glycemic control, HbA1C, basal insulin, insulin resistance, total and low-density lipoprotein cholesterol, and triglycerides were significantly reduced after 90-day treatment with combination of B. aristata extract and Silybum marianum extract." (PMID 23737828, 2013). "Further clinical investigations will be required to establish whether glucose, insulin or insulin-resistance per se can modulate plasma NOV." (PMID 23785511, 2013). "The HOMA-IR score was calculated from fasting blood glucose and insulin concentration to assess whether AKGs diet protected mice from insulin resistance." (PMID 23864898, 2013). "Based on these results, we hypothesized that the insulin resistance index based on C-peptide levels may be superior to an index based on insulin levels measured during a MTT." (PMID 23339473, 2013). "However, they do exhibit increased insulin sensitivity and resistance to dexamethasone-induced insulin resistance." (PMID 24339790, 2013). "In addition, the Tai Chi group also showed a significant decrease in fasting insulin and a decrease in homeostasis model assessment of insulin resistance (HOMA) index, which is suggestive of improved insulin resistance." (PMID 24159346, 2013). "The disturbance in the attraction for lipids found in DIO mice appears to be independent of obesity-associated insulin resistance because a correlation between preference for fat and plasma insulin levels is lacking." (PMID 23840049, 2013). "Elevated plasma TNF-α levels may play an important role in insulin resistance by impairing insulin signaling." (PMID 23437347, 2013). "Insulin resistance is an important aspect of glucose metabolism and implies that only a small amount of glucose is cleared from the extracellular fluid in response to any given insulin secretion." (PMID 24188443, 2013). "In fact, when heterozygous C3H-11NSY mice in the present study were compared with our previous data of C3H mice, insulin secretion was significantly impaired and insulin resistance was marginally stronger in heterozygous C3H-11NSY mice (P < 0.05 and P = 0.07, resp.; Mann-Whitney U test)." (PMID 23671880, 2013). "The link between long-chained PUFA composition in skeletal muscle PL and whole-body insulin sensitivity, which is suggested by human studies, might be coinciding with obesity induced whole-body insulin resistance." (PMID 23755234, 2013).
Insulin resistance (continued). "Others have shown that GLUT4 content decreases along with the development of insulin resistance in the myocardium and other insulin sensitive tissues which might play a key role in the impaired glycemic homeostasis in metabolic syndrome." (PMID 23320804, 2013). "Fasting glucose significantly increased by an average of 7.0 mg/dL [range +31 mg to -6 mg/dL; p = 0.02], analogous increases were observed for fasting insulin at 5.7 μU/ml [range +22.9 to +0.6 μU/ml; p = 0.04] and insulin resistance [HOMA-IR +1.6; range +8.0 to +0.2; p = 0.04]." (PMID 23347533, 2013). "Thus it is not merely an increased mass of adipose tissue that directly leads to attenuation of insulin action, but rather adipose tissue inflammation activated by the immune system in obese individuals that leads to insulin resistance." (PMID 23577240, 2013). "Recent evidence suggests that cultured sensory neurons from insulin-resistant mice display classic signs of insulin resistance and that insulin resistance may be contributing to mitochondrial dysfunction and increased ROS in DN." (PMID 24252636, 2013). "However, there were statistically significant differences in mean glucose and insulin levels, homeostasis model assessment for insulin resistance, LDL and high-density lipoprotein values, and highly significant differences in mean triglyceride values." (PMID 24072084, 2013). "In rodent models, circulating RBP4 correlates positively with insulin resistance and RBP4 directly induces insulin resistance presumably by increased expression of the hepatic gluconeogenic enzyme phosphoenolpyruvate carboxykinase and impaired skeletal muscle insulin signaling." (PMID 23781325, 2013). "Exercise can prevent lipid-induced insulin resistance, and the form the lipid is stored in may contribute to insulin resistance, asceramide or diacylglycerol are more detrimental to cellular insulin action than triglyceride." (PMID 24772374, 2013). "Higher insulin concentration suggests the increase of insulin resistance." (PMID 23857218, 2013). "A variety of molecules have been associated with contributing to insulin resistance, when target cells no longer respond to insulin signals to take up glucose from the blood, resulting in high blood glucose and energy-deprived tissues." (PMID 24499129, 2013). "Indeed, a profound state of insulin resistance has been found in the hearts of ob/ob mice and the ability of these hearts to modulate substrate utilization in response to insulin and changes is altered." (PMID 24106479, 2013). "In addition, both LP and BB peel extracts also improved glucose tolerance and insulin resistance or serum insulin contents in the HF diet-induced mice." (PMID 24147098, 2013). "In a more complicated system with a combined hypertension and insulin resistance, insulin and RAS may cross-talk with each other." (PMID 25340140, 2013). "Therefore, the data presented in this study suggested that (10- and 12-(Z,E)-HODE)/LA reflected insulin secretion from pancreatic β-cells and insulin resistance and then correlated very well with plasma levels of glucose during OGTT." (PMID 23691063, 2013). "Understanding how insulin dysregulation relates to brain function may help characterize the pathways through which insulin resistance may lead to cardiovascular autonomic impairments and associated risk for adverse disease outcomes and premature mortality." (PMID 24358272, 2013). "Neurons are insulin-dependent metabolically active tissues, like fat and muscle, that develop insulin resistance and thus cannot respond properly to the neurotrophic properties of insulin, resulting in neuronal injury, subsequent dysfunction and ultimately Alzheimer’s and related diseases." (PMID 24349472, 2013). "Insulin resistance and obesity are highly correlated, and thus by deliberately minimizing the confounding influence of obesity, those scans maximized the chances of identifying insulin secretion genes." (PMID 23997649, 2013).